TEDC2 (tubulin epsilon and delta complex 2)
Description:
Acts as a positive regulator of ciliary hedgehog signaling. Required for centriole stability.
Synonyms: C16orf59; FLJ13909
Tractability: PROTAC: ubiquitination databases record sites on it.
Gene: Protein-coding gene on chromosome 16 (2,460,086 to 2,464,963, forward strand). Ensembl gene ENSG00000162062.
Subcellular location: Cell projection, cilium; Cytoplasm, cytoskeleton, microtubule organizing center, centrosome, centriole
Subcellular location (Human Protein Atlas): Cell Junctions; Nucleoplasm
Gene Ontology:
Molecular function: protein binding
Biological process: cytoskeleton organization; microtubule cytoskeleton organization; positive regulation of smoothened signaling pathway
Cellular component: centrosome; centriole; cilium
Genetic constraint (gnomAD): Loss-of-function variants: 50 observed, 42.69 expected, observed/expected ratio (o/e) 1.17, 90% interval 0.93 to 1.48. The synonymous counts are far from expectation, so gnomAD's model fits this gene poorly and the ratio says little. Missense variants: 631 observed, 533.82 expected, observed/expected ratio (o/e) 1.18, 90% interval 1.11 to 1.26. Synonymous variants: 299 observed, 232.12 expected, observed/expected ratio (o/e) 1.29, 90% interval 1.17 to 1.42.
Homologues: Orthologues: chimpanzee TEDC2 (98% identical), macaque TEDC2 (80% identical), pig TEDC2 (71% identical), dog TEDC2 (69% identical), guinea pig TEDC2 (65% identical), mouse Tedc2 (62% identical), rat Tedc2 (58% identical), tropical clawed frog tedc2 (29% identical).
Diseases named in the same sentence as TEDC2 in open-access papers:
TEDC2 is named in the same sentence as 14 diseases in open-access papers, as found by Europe PMC text mining. Sharing a sentence is not in itself a finding about the gene and the disease. The quoted sentences say what the papers report.
lung adenocarcinoma (6 papers, 2015 to 2024). A carcinoma that arises from the lung and is characterized by the presence of malignant glandular epithelial cells. "Among them is TEDC2 (also known as C16orf59) whose increased expression is associated with poor prognosis of lung adenocarcinoma." (PMID 39189258, 2024). "This study aimed to identify the role of TEDC2 in prognosis and immune microenvironment of lung adenocarcinoma (LUAD)." (PMID 36973475, 2023). "Moreover, nomogram models were formulated using three distinct tumours, namely kidney renal clear cell carcinoma (KIRC), lung adenocarcinoma (LUAD), and liver hepatocellular carcinoma (LIHC), to evaluate the prognostic significance of TEDC2 in tumours." (PMID 38239349, 2023).
schizophrenia (3 papers, 2014 to 2023). A major psychotic disorder characterized by abnormalities in the perception or expression of reality. "TEDC2 was also seemed to act as a potential marker for treatment effect in male schizophrenia patients." (PMID 36973475, 2023).
central nervous system lymphoma (2 papers, 2023). "Previous studies reported that TEDC2 could highly express in central nervous system lymphoma and might contribute to the tumorigenesis of LUAD10,11, but the prognostic and immune features of TEDC2 in LUAD have not been comprehensively characterized." (PMID 36973475, 2023).
laryngeal squamous cell carcinoma (2 papers, 2023). A squamous cell carcinoma that arises from the larynx. "TEDC2 has been identified as a potential oncogenic gene linked to immune infiltration in the tumor microenvironment in two recent studies focusing on hepatocellular carcinoma and laryngeal squamous cell carcinoma." (PMID 38239349, 2023). "Such genes are represented by LC35C1, HOXB7, and TEDC2, and they have the potential to become new therapeutic targets and prognostic biomarkers for laryngeal squamous cell carcinoma." (PMID 36981644, 2023).
adrenocortical carcinoma (1 paper, 2023). "The abnormal expression of TEDC2 can predict survival outcomes in patients with adrenocortical carcinoma (ACC), KIRC, kidney renal papillary cell carcinoma (KIRP), LUAD, LIHC, lower grade glioma (LGG), and thymoma (THYM)." (PMID 38239349, 2023).
cholangiocarcinoma (1 paper, 2023). A carcinoma that arises from the intrahepatic biliary tree (intrahepatic cholangiocarcinoma) or from the junction, or adjacent to the junction, of the right and left hepatic ducts (hilar cholangiocarcinoma). "We found that all cholangiocarcinoma cases with genetic alteration (~3% frequency) had miss mutation of TEDC2, and adrenocortical carcinoma tumor samples had the highest TEDC2 genetic alteration frequency (>4%)." (PMID 38239349, 2023).
lung carcinoma (1 paper, 2023). "Besides, TEDC2 expression was also correlated with TNFRSF25, TNFRSF4 and TNFRSF18 in our analysis, which might be correlated with immune evasion and poor outcome in lung cancer, but the molecular mechanisms of these immune checkpoint molecules still remain elusive and need further investigation." (PMID 36973475, 2023).
skin cancer (1 paper, 2023). "We also found genes that, to our knowledge, have no previously reported driver NCVs with TFA-BT NCVs in at least 5% of tumors within certain cancer types, such as RPL13A (bladder and skin cancer), TEDC2 (skin cancer), and PES1 (skin cancer)." (PMID 36808133, 2023).
cancer (5 papers, 2021 to 2024). A tumor composed of atypical neoplastic, often pleomorphic cells that invade other tissues. "Consistent with the findings of high expression of these genes in different cancer types, our study found that TEDC2 and three other diagnostic markers were overexpressed in LUAD tissues and showed high diagnostic accuracy for LUAD." (PMID 39553728, 2024). "Using pan-cancer data, Cox regression analysis identified TEDC2 high expression as an independent risk factor for poor prognosis in tumors." (PMID 38239349, 2023). "However, the biological significance of TEDC2 in pan-cancer is unclear." (PMID 38239349, 2023). "In comparison with the other two prognostic genes, TEDC2 has not been intensively investigated in cancer." (PMID 35087752, 2021). "Currently, there are no reports on the role of TEDC2 in pan-cancer." (PMID 38239349, 2023). "In addition to the reported genes related to cancer cell stemness, our results also showed many genes that had not been reported to be related to cancer cell stemness, especially to PCa cell stemness, such as TEDC2, TMEM132A, and VARS, etc." (PMID 33985534, 2021).
tumor (5 papers, 2021 to 2026). "A total of 76 TEDC2 mutations, including 13 truncating mutations, 57 missense mutations, 4 splice mutation and 2 fusion mutations were detected in TCGA tumor samples." (PMID 38239349, 2023). "The diagnostic value of TEDC2 was determined by ROC curve analyses which were performed between tumor tissues with different stage and normal tissues." (PMID 36973475, 2023). "We found that TEDC2 expression was negatively associated with the levels of some marker sets marking DC, B cell, tumor-associated macrophage (TAM), monocyte and neutrophil." (PMID 36973475, 2023). "In the future, detailed mechanism research still needed to elucidate the association of TEDC2 and tumor." (PMID 35087752, 2021). "According to immune infiltration analysis, TEDC2 expression was associated with multiple immune cells, and might affect tumor survival." (PMID 38239349, 2023). "To establish a quantitative prognostic approach for diverse tumor patients, we initially identified, via unvaried Cox analysis, a significant association between the prognosis of multiple tumor patients and the expression of TEDC2, age, and T stage." (PMID 38239349, 2023). "In addition, we assessed whether genetic variation of TEDC2 is associated with clinical survival prognoses with different types of tumor." (PMID 38239349, 2023). "Subsequently, we investigated the association between TEDC2 expression and DSS and PFI in tumours, which was roughly in agreement with the result of OS." (PMID 38239349, 2023). "Concurrently, TEDC2 knockdown significantly curtails the migratory and invasive capabilities of tumor cells." (PMID 38239349, 2023). "The outcomes revealed a significant reduction in both migration and invasion abilities of the tumor cells following TEDC2 knockdown." (PMID 38239349, 2023). "Suppression of TEDC2 effectively impedes the cell cycle progression of tumor cells during the G1 phase, consequently impeding cell proliferation." (PMID 38239349, 2023). "We analyzed the effect on tumor survival by combining the expression of TEDC2 and immune cell infiltration." (PMID 38239349, 2023). "In this study, we employed R software and various online bioinformatics analysis tools to investigate the functional attributes of TEDC2 in human tumours and its potential involvement in immune response." (PMID 38239349, 2023). "Based on these results, it can be concluded that TEDC2 not only is an overexpressed gene but also serves as a significant prognostic factor for tumor patients." (PMID 38239349, 2023). "To elucidate the biological function of TEDC2 in tumors, we used GEPIA2 to obtain the top 100 genes with similar expression patterns for TEDC2 in all tumor types." (PMID 38239349, 2023). "Differential analysis revealed that 16 tumour types expressed TEDC2 to a greater extent than normal tissues." (PMID 38239349, 2023). "Subsequently, we conducted a detailed analysis in LIHC on the correlation between tumor immune related cytokines and immune checkpoints with TEDC2." (PMID 38239349, 2023). "The status of TEDC2 expression was evaluated in samples from the TCGA and GEO datasets, as well as in tumour and corresponding normal samples from the TCGA database." (PMID 38239349, 2023). "In this study, we conducted a thorough analysis by utilizing an open-access database to investigate the prognostic significance and carcinogenic mechanism of TEDC2 across diverse tumor types." (PMID 38239349, 2023). "In our study, we found that TEDC2 expression was negatively correlated with most infiltrated immune cells, including DC cells, macrophages, CD8 T cells, cytotoxic cells, NK cells and eosinophils, suggesting that TEDC2 might induce tumor immunosuppression." (PMID 38239349, 2023). "The results showed TEDC2 expression correlated positively with these genes, suggesting that TEDC2 may be involved in tumor growth." (PMID 38239349, 2023).
tumor (continued). "Then, we validated whether knocking down TEDC2 can inhibit the malignant biological behavior of tumor cells in two cell lines, A549 and HepG2." (PMID 38239349, 2023). "We observed the genetic alteration status of TEDC2 in different tumor samples of the TCGA cohorts." (PMID 38239349, 2023). "TEDC2 has been identified as a potential therapeutic target that could predict the prognosis of multiple tumour types, making it a promising target for reversing tumour development." (PMID 38239349, 2023). "In order to substantiate these findings, we conducted an analysis of the immunohistochemistry of TEDC2 across various tumors within the HPA database, results demonstrated that a noteworthy increase in the expression of the TEDC2 protein within certain tumor samples." (PMID 38239349, 2023). "To investigate whether TEDC2 could serve as a prognostic marker for tumors, we examined the correlation between TEDC2 expression and the prognosis of different tumor patients." (PMID 38239349, 2023). "Interfering TEDC2 expression inhibited tumor cell proliferation and migration." (PMID 35087752, 2021). "Subsequent results indicated that TEDC2 has the ability to influence ECM regulators, cell cycle, and Immune checkpoint-associated signalling pathways, which could potentially lead to a poor prognosis and tumour progression." (PMID 38239349, 2023). "Therefore, as a tumor-promoting gene, TEDC2 may increase in the condition of alcohol consumption and thus promote tumorigenesis and metastasis." (PMID 35087752, 2021). "Among these genes, EFNA4 and TEDC2 were significantly upregulated, whereas CDC42EP2, STX11, THBD, TMEM88, and GPM6A were notably downregulated in tumor tissues compared with adjacent normal tissues." (PMID 42196266, 2026). "In addition, ROC curve analysis found that TEDC2 could distinguish patients with LUAD from the normal population regardless of tumor stage." (PMID 36973475, 2023). "Notably, the negative correlations of four key markers, UBE2T, TEDC2, RCC1, and FAM136A, with stromal, immune, and ESTIMATE scores suggest that the high expression of these genes in LUAD may contribute to tumor growth and malignant behaviors by inhibiting the role of stromal and immune cells." (PMID 39553728, 2024).
TEDC2 also shares sentences with these, for which no sentence is quoted: diffuse large B-cell lymphoma (1 paper); glioma (1); hepatocellular carcinoma (1); thymoma (1).